STAT3 (signal transducer and activator of transcription 3)
Diseases named in the same sentence as STAT3 in open-access papers (continued):
Sharing a sentence is not in itself a finding about the gene and the disease.
tumor (continued). "Restoring immune cell homeostasis and suppressing pro-tumor phenotypes through pharmacological inhibition of the key signaling nodes such as STAT3 may complement existing cancer therapies." (PMID 41514627, 2025). "STAT3 serves as a key transcriptional factor in regulating tumor energy metabolism." (PMID 41145734, 2025). "In addition, increased activity of the transcription factors NFκB and STAT3 was observed in NK cells, further promoting their effector functions and survival within the tumour environment." (PMID 41284319, 2025). "Additionally, STAT3 supports tumor cell survival and enhances the recruitment of other immune suppressive elements into the TME." (PMID 40281554, 2025). "STAT3 signaling regulates antitumor immunity and promotes an immunosuppressive tumor environment." (PMID 40246812, 2025). "HT inhibited the proliferation of Panc02 cells through the STAT3/Cyclin D1 signaling pathway and in HT-treated tumor-bearing mice, orthotopic PDA tumors were suppressed, with a reduction in myeloid-derived suppressor cells (MDSCs) and an increase in M1 macrophages." (PMID 40427617, 2025). "Mechanistically, LPS activates the signal transducer and activator of transcription 3 (STAT3), inducing cells to produce vascular endothelial growth factor and promoting both tumor cell proliferation and angiogenesis in HCC tissues, thereby accelerating malignant progression." (PMID 41440201, 2025). "Furthermore, nanoparticle-based drug delivery technologies provide tailored STAT3 regulation in the tumour microenvironment, reducing systemic toxicity and increasing therapeutic effectiveness." (PMID 40350446, 2025). "However, evidence suggests that STAT1 also emphasizes tumor-promoting functions, while STAT3 also acts as a tumor suppressor protein targeting genes involved in apoptosis and growth arrest." (PMID 39942749, 2025). "Furthermore, therapeutic targeting of STAT3 in neutrophils, both in vitro and in vivo, amplified their capacity to activate cytotoxic T cells and promote effective tumor cell killing." (PMID 40885734, 2025). "Given the pivotal role of the IL-6/STAT3 axis in promoting tumor growth, survival, and inflammatory signaling, this robust inhibition indicates that KAE exerts potent anti-inflammatory and anticancer activity, nearly matching the efficacy of the standard chemotherapeutic." (PMID 41515404, 2025). "Additionally, COX-2, a downstream mediator of NF-κB involved in tumor-promoting inflammation, serves as a STAT3 activator." (PMID 40420174, 2025). "STAT3 protein levels were significantly higher in tumor with high PD-L1, and the proportion of STAT3-positive cells was markedly elevated compared to the low PD-L1 group, further supporting STAT3 involvement in the high PD-L1 tumors." (PMID 41446744, 2025). "CAFs-derived IL-6 may promote tumor proliferation by regulating osteopontin expression in a STAT3-dependent manner." (PMID 40136652, 2025). "IL-6 is an inflammatory mediator that also activates STAT3 and promotes tumor progression." (PMID 40759869, 2025). "Osteopontin (OPN), a secreted extracellular matrix protein, that interacts with Integrins, functions as a Th1 cytokine, is involved in tissue remodeling and intricately linked to the JAK2/STAT3 and PI3K/Akt signaling pathways in HCC, contributing to tumor growth, invasion, and metastasis." (PMID 40269686, 2025). "Multiple recent investigations have shown that signal transducer and activator of transcription (STAT3) is active by default in a variety of malignant tumors and tumor cell lines, including breast cancer, prostate cancer, pancreatic adenocarcinoma, colon carcinoma, and GC." (PMID 40350446, 2025).
tumor (continued). "However, chronic overexpression of CDC25C upregulates PD-L1 in tumor cells through the STAT3/IRF1 pathway, and promotes the recruitment of Tregs, MDSCs and M2-like macrophages (M2) via chemokines such as CXCL10." (PMID 41019083, 2025). "In CC-LR mice, STAT3 inhibition attenuated tumor burden and tumor proliferation." (PMID 40356899, 2025). "Thus, the inhibition of STAT3 is an important anti-tumor approach and likely one of the major mechanisms through which HO-3867 is inhibiting cell growth in these experiments." (PMID 40915175, 2025). "This amplified inflammation may promote the survival and proliferation of microscopic tumor foci through IL-6/STAT3 activation, leading to rapid polyp development." (PMID 40650003, 2025). "STAT3 is often activated in immune cells infiltrating tumours." (PMID 40407951, 2025). "Furthermore, lncRNA-ATB promotes the autocrine induction of IL-11 by binding to IL-11 mRNA, activating the STAT3 signaling pathway, and further facilitating the organ colonization of disseminated tumor cells." (PMID 40352941, 2025). "Recent studies have demonstrated that lactylation drives the downregulation of retinoic acid receptor gamma (RARγ) in TAMs, thereby enhancing IL‐6 levels in the TME and promoting tumor growth and proliferation through the activation of STAT3 signaling in colorectal tumor cells." (PMID 40443721, 2025). "Furthermore, what makes STAT3 a promising target is that it plays a crucial role in tumor-stromal cells including immune cells in maintaining an immune-suppressive tumor immune microenvironment (TME) to support and promote tumor progression." (PMID 40529368, 2025). "In vivo, verteporfin treatment effectively reduced tumor burden in the HR xenograft models, decreased p-STAT3 and PD-L1 expression, and increased apoptosis, underscoring the therapeutic potential of targeting the ROR2-YAP/TEAD axis to overcome trastuzumab resistance." (PMID 40542295, 2025). "Additionally, sublytic levels of MAC deposition can activate intracellular signaling pathways, including PI3K/Akt, MAPK/Erk, and NF-κB/STAT3, leading to enhanced tumor cell proliferation, survival, and upregulation of drug efflux transporters." (PMID 40806542, 2025). "Moreover, tumor-derived cytokines, such as G-CSF and GM-CSF, activate downstream signaling pathways, particularly STAT3 and STAT5, which drive the expression of lipid transport receptors such as CD36 on MDSCs." (PMID 40361394, 2025). "Notably, the activation of STAT3 is crucial for tumor growth as it enhances the expression of PD-L1 on tumor cells." (PMID 40739089, 2025). "Notably, studies have shown that ITGA2 overexpression upregulates PD-L1 expression through activation of the STAT3 signaling pathway in several malignant tumor cells, providing direct evidence for ITGA2-mediated remodeling of the immune microenvironment." (PMID 40940943, 2025). "They showed that STAT3 overexpression promoted tumor growth and was able to partially negate the inhibitory effects of miR-4458 overexpression on tumor growth, whereas PD-L1 knockdown was able to neutralize the growth-promoting effects of STAT3 overexpression." (PMID 39343796, 2024). "Finally, STAT3 activity has been shown to confer resistance to chemotherapeutic drugs in multiple tumor cell lines and xenograft models." (PMID 38339245, 2024). "Furthermore, within the GBM TME, activation of both STAT3 and C/EBPβ propagated tumor necrosis and hypoxia." (PMID 38891074, 2024). "Blocking STAT3 activation in patients with stromal-rich tumors could suppress these hallmarks of cancer and prevent tumor progression." (PMID 38424636, 2024). "Previous studies on the abnormal expression of FGL1 in tumor tissues have suggested that the IL6/Stat3 signaling pathway, YY1, HNF1a, and other factors may affect the transcription of FGL1." (PMID 39085849, 2024).
tumor (continued). "In contrast, differentially expressed genes between CECs isolated using the cmHsp70.1 mAb- versus EpCAM mAb-based approach, such as ROCK2, STAT3 and CD82, are related to EMT, stemness and endometrial cell proliferation, which are regulated via up-regulated CD44/STAT3 signaling in tumor cells." (PMID 39519195, 2024). "Notably, within the realm of tumor metastasis, treatment with vitamin D has been demonstrated to selectively inhibit the expression of p-STAT3, zinc finger E-box binding homeobox 1 (Zeb1), and Vimentin while enhancing the expression of E-Cadherin." (PMID 38920657, 2024). "Indeed, research derived from the Cancer Genome Atlas (TCGA) database proved that the IL-6R/STAT3/miR-34a loop is active in primary human CRCs, contributing to a mesenchymal phenotype of tumor cells, along with invasion and metastasis." (PMID 38256960, 2024). "Notably, IL-6 can elevate the levels of EIF4A3 and CCL2 in tumor cells via activation of the JAK2/STAT3 pathway, further facilitating tumor cSERPINE2 biogenesis and inducing TAMs recruitment." (PMID 38397395, 2024). "We summarize both the positive and negative modulators of STAT3 together with the cancer hallmarks involving activities regulated by STAT3 and highlight its extremely sophisticated regulation on immunosuppression in tumor microenvironment and metabolic reprogramming." (PMID 38245798, 2024). "Moreover, tumor cells partially rely on the IL-6/STAT3 axis to escape cell death induced by cytotoxic drugs." (PMID 38520006, 2024). "Therefore, the epistatic relationship between SMAD4 and STAT3 has implications for tumor aggressiveness, metastatic propensity, and therapeutic resistance." (PMID 38573819, 2024). "Additionally, immunofluorescence analysis showed a lower MVD with decreased CD34 and CD31 expression in knocked down STAT3 tumor-bearing tissues." (PMID 38939041, 2024). "STAT3 is a key transcription factor mediating inflammatory and immune responses, and while inhibition of STAT3 within tumor cells may be clinically beneficial, blocking STAT3-mediated immunity may negate this effect." (PMID 38297352, 2024). "Activated STAT3 within the tumor microenvironment induces the malignant transformation of relevant cells to immunosuppressive forms, such as M2-like tumor-associated macrophages, Tregs, and cancer-associated fibroblasts, thereby promoting cancer growth, expansion, and infiltration." (PMID 38834900, 2024). "Furthermore, in a patient-derived xenograft (PDX) tumor model, high expression of WNT7A and phosphorylated STAT3 was observed, which positively correlated with tumor progression." (PMID 38246919, 2024). "In addition, STAT3 inhibitor treatment in HONE1 tumor-bearing BALB/c nu/nu mice synergistically increased the effect of radiation or cisplatin, as evidenced by reduced tumor volumes." (PMID 38720107, 2024). "In contrast, STAT3 promotes angiogenesis, thereby supporting tumor progression and metastasis." (PMID 38816668, 2024). "In CRC, STAT3 affects T cell activity by inhibiting the function of antigen-presenting cells, and when STAT3 expression is inhibited, the tumor cells’ ability to evade the immune system is weakened, allowing the immune system to more effectively recognize and eliminate cancer cells." (PMID 39830506, 2024). "Accordingly, blocking the STAT3 activity in tumor cells leads to the maturation of dendritic cells." (PMID 38245798, 2024). "Because the group 2 was characterized by tumor-FKBP51s expression significantly higher than that of group 1 (bottom), we investigated whether FKBP51s regulated STAT3 activation, a transcription factor that sustains GBM-induced immunosuppression." (PMID 38651817, 2024). "Future studies may explore how different types of tumor-derived EVs vary in their ability to modulate the JAK/STAT3 pathway and promote angiogenesis." (PMID 39596828, 2024).
tumor (continued). "It seems contradictory for tumor tissues to simultaneously up-regulate and down-regulate the STAT3 activity of myeloid cells, but a dynamic hypothesis can be put forward when considering time and space." (PMID 38279145, 2024). "Consequently, tumor cell-induced activation of GM-CSF-driven Sp1 and STAT3 cooperatively trigger the expression of target genes, facilitating the immunosuppressive functions of MDSCs." (PMID 38983795, 2024). "Apart from the canonical activities of STAT3 in pleiotropic effects on a spectrum of tumor processes, STAT3 also functions as a hub for energy and matter metabolism via its different subcellular activities such as nuclear, mitochondrial, and cytoplasmic STAT3 activities." (PMID 38245798, 2024). "STAT3 also promotes tumor immune evasion by upregulating immune checkpoint proteins." (PMID 38339245, 2024). "Additionally, they can act on tumor cells by activating the STAT3 pathway, promoting their growth and immune evasion." (PMID 38892375, 2024). "In TME, the crosstalk of STAT3 and NF-κB pathways promotes an important role in modulating cancer-associated inflammation-promoting TAM polarization towards M2, as well as stimulating resistance to apoptosis, EMT, invasion, and proliferation in tumor cells." (PMID 39061137, 2024). "Analogously, in comparison to EGCG alone, combined administration of EGCG and curcumin better attenuated the evolution of normal ECs to TECs stimulated by tumor medium supernatant or tumor tissue homogenate through inhibiting the JAK/STAT3/IL-8 pathway, thereby reversing endothelial angiogenesis." (PMID 38348027, 2024). "Furthermore, in an in vivo periodontitis model with chemically induced tumorigenesis, chronic co-infection of P. gingivalis and F. nucleatum increased tumor size and invasion capacity via the IL-6/STAT3 axis." (PMID 38612423, 2024). "Therefore, we first aimed to study the pharmacodynamics of a STAT3-inhibitor Napabucasin in low vs high MUC1 tumor cells in vitro." (PMID 38326371, 2024). "Moreover, AKR1C3 regulates and activates NF-κB by inducing autoubiquitination of TRAF6, subsequently releasing proinflammatory factors that enhance STAT3 phosphorylation, fostering increased tumor cell proliferation and invasion." (PMID 38523637, 2024). "Moreover, TAMs regulate breast cancer stem cell phenotype and promote tumor growth via the EGFR/Stat3/Sox-2 signaling pathway." (PMID 38840908, 2024). "Moreover, the levels of phosphorylated JAK1/2 and STAT3 proteins were significantly lower in the tumours dissected from the shIGFBP7 group than in those from the shNC group." (PMID 39351597, 2024). "STAT3 was reported to cooperate with GR or p65 to drive gene expression in tumor cells and T cells." (PMID 38238297, 2024). "However, subsequent to the confirmation of ACKR3 as a receptor of CXCL12, a plethora of studies have verified that the binding of CXCL12 and ACKR3 can also activate the STAT3 pathway, thereby fostering tumor development." (PMID 38920657, 2024). "In line with this hypothesis, immunofluorescent analysis of murine orthotopic PDAC tumours revealed an overall decrease in the expression of pSTAT3Tyr705 in both TAMs (F480+/pSTAT3+ cells) and CAFs (αSMA+/STAT3+ cells) upon IGF blockade." (PMID 39165364, 2024). "Activated Stat3 can upregulate the expression of anti-apoptotic factors, such as Bcl-2 and Bcl-xL, and downregulate the expression of pro-apoptotic factors, such as Bax, Bad, and Bid, to participate in tumor development." (PMID 39203920, 2024). "JAK2/STAT3 is a classical signaling pathway in tumor research." (PMID 38420199, 2024). "However, genetic ablation of mouse Stat3 in endothelial cells inhibited tumor angiogenesis and the growth of colorectal cancer and melanoma in mice, thus phenocopying the effects of Yap/Taz deletion." (PMID 38538573, 2024). "Additionally, the transcription factor STAT3 plays a significant role in forming the tumor microenvironment." (PMID 38844562, 2024).
tumor (continued). "STAT3 interacts with products such as IL-6 receptors and epidermal growth factor receptor, expressed via a receptor, and promotes growth differentiation of tumor cells while inhibiting tumor cell death." (PMID 39590337, 2024). "Taken together, our results show that targeting VPS35- and IL-6/STAT3-mediated tumour interactions may be an attractive therapeutic strategy for GC." (PMID 37950040, 2024). "Besides, we identified that a clinical anti‐inflammatory drug alminoprofen targeted C21orf58, displayed an attractive anti‐tumor efficacy on HCC treatment by preventing the formation of JAK2/C21orf58/STAT3 complex, resulting in suppression of STAT3 cascades." (PMID 38342622, 2024). "Similarly in models of non-small cell lung cancer (NSCLC) culturing tumor cells with primary CAFs induces STAT3 in the tumor cells and induces EMT." (PMID 38424636, 2024). "Furthermore, TNKS1BP1 knockdown synergized with anti-PD-L1 treatment by upregulating PD-L1 expression on tumor cells via the JAK2/STAT3 pathway and augmenting the infiltration and effector function of cytotoxic T lymphocytes." (PMID 39019859, 2024). "While the oncogenic role of STAT3 is well studied, evidence suggests that STAT3 demonstrates tumor-suppressive functions in certain cancers and this dual role may depend on inherent genomic mutations." (PMID 38339245, 2024). "By negatively regulating the pro-tumorigenic signaling pathway STAT3 in microglia, rutin may have significant implications in suppressing tumor progression." (PMID 38248305, 2024). "Additionally, the CCL18/PITPNM3 axis has been shown to activate the JAK2/STAT3 signaling pathway, a conserved pathway involved in tumor growth and metastasis." (PMID 39409924, 2024). "Dp may exert its anti-TNBC effects by downregulating PD-L1 expression in TNBC cells and exosomes through the JAK2/STAT3 signaling pathway, potentially restoring T cell activity and modifying the tumor microenvironment." (PMID 39781272, 2024). "Furthermore, to elucidate the involvement of STAT3 in PCa, the levels of STAT3 were evaluated in tumor tissues from patients with PCa, revealing a noteworthy upregulation of STAT3 expression in PCa tissues." (PMID 39132168, 2024). "The expression of Twist1 in tumor cells is modulated by several regulators including signal transducer and activator of transcription 3 (STAT3), nuclear factor kappa B (NF-κB), steroid receptor co-activator 1 (SRC1), Msh homeobox protein (MSX2), and Hypoxia-inducible factor 1-alpha (HIF-1α)." (PMID 38791037, 2024). "In lymphocytic leukemia, various aberrant signaling pathways in tumor microenvironment, including ZAP-70 protein, MAPK, and STAT3, stimulate the expression of post-translational regulator microRNA (miR-21) and other tumor suppressor genes (PTEN, PDCD4, and PIAS3)." (PMID 38590645, 2024). "The activation of the STAT3 pathway, whether through intrinsic or extrinsic mechanisms, exerts a profound influence on the tumor microenvironment." (PMID 38920657, 2024). "Phosphorylated STAT3 (pSTAT3) was upregulated in BMDMs treated with Se CM compared to CM from normal tumor cells (Ctrl), which could be rescued by IL-6-neutralized CM." (PMID 38323313, 2024). "Moreover, IL-6 released in the TME also suppresses the differentiation of IFN-γ-producing TH cells by attenuating both surface expression of MHC-II and secretion of IL-12 in dendritic cells of tumor-bearing mice, in a STAT3-dependent manner." (PMID 39281678, 2024). "These implicates that HLJ1 might suppress tumor metastasis and outgrowth by inhibiting STAT3 activation and preventing premetastatic myeloid cell colonization." (PMID 39738726, 2024).